FAM13A (family with sequence similarity 13 member A)
Diseases named in the same sentence as FAM13A in open-access papers (continued):
Sharing a sentence is not in itself a finding about the gene and the disease.
Insulin resistance (7 papers, 2016 to 2025). Increased resistance towards insulin, that is, diminished effectiveness of insulin in reducing blood glucose levels. "In addition, recent studies have implicated HNF4A and PROX1-AS1 in insulin resistance and T2D, whereas loci harboring FAM13A, RSPO3, and EBPL have been associated with body fat distribution and hepatic steatosis." (PMID 39796632, 2025). "Family with sequence similarity 13 member A (FAM13A), which is involved in adipocyte differentiation and lipid metabolism, may reflect maladaptive metabolic responses that are closely linked to insulin resistance and renal lipotoxicity." (PMID 40868959, 2025). "This selective role of FAM13A is supported by the SAT-specific FAM13A eQTLs that are associated with a metabolically obese normal weight phenotype and by the correlation of SAT FAM13A expression with a range of insulin resistance-related phenotypes." (PMID 32193374, 2020). "Here, we demonstrate that in humans, FAM13A alleles are associated with increased FAM13A expression in subcutaneous adipose tissue (SAT) and an insulin resistance-related phenotype (e.g. higher waist-to-hip ratio and fasting insulin levels, but lower body fat)." (PMID 32193374, 2020). "Furthermore, while experiments in the model systems will be required to validate many of the most promising targets, some genes such as FAM13A and PDGFC have already been partially validated within the context of insulin resistance." (PMID 35292083, 2022).
idiopathic pulmonary fibrosis (6 papers, 2016 to 2025). Idiopathic pulmonary fibrosis (IPF) is a nonneoplastic pulmonary disease that is characterized by the formation of scar tissue within the lungs in the absence of any known cause. "Diseases associated with FAM13A include polycystic kidney disease 2 with or without polycystic liver disease and interstitial lung disease." (PMID 37019990, 2023).
Obesity (6 papers, 2019 to 2025). Accumulation of substantial excess body fat. "Other genetic variants associated with obesity are FAM13A gene (Family With Sequence Similarity 13 Member A) polymorphisms." (PMID 37107672, 2023). "FAM13A has previously been associated with cardiometabolic diseases and obesity-related conditions." (PMID 40868959, 2025). "FAM13A in the region on chromosome 6 associated with adult August weight has been found to modulate body fat distribution and adipocyte function in humans and mice affects adipose insulin signaling in mice and is associated with obesity also in mice." (PMID 36532132, 2022). "Murine FAM13A expression was nutritionally regulated and dramatically reduced in epididymal and subcutaneous fat in genetic and diet-induced obesity." (PMID 30301961, 2019). "However, the function of FAM13A in adipose development and obesity remains largely uncharacterized." (PMID 30301961, 2019). "The negative correlation of adipose Fam13a expression with obesity in a genetically obese and diabetic mouse dataset of BTBRob/ob was demonstrated through a collaboration with Dr. Alan Attie’s lab." (PMID 32193374, 2020). "Despite its association with fat distribution, to date, no study has explored the potential role of FAM13A in regulating adipogenesis and obesity." (PMID 30301961, 2019).
chronic lung disease (5 papers, 2017 to 2020). According to the definitions of the American and British Thoracic Societies, including pulmonary functional tests, X-rays, and CT scans for items such as fibrosis, bronchiectasis, bullae, emphysema, nodular or lymphomatous abnormalities. "Previous genome-wide association studies suggest a strong association between FAM13A and chronic lung diseases." (PMID 32053709, 2020). "The WHRadjBMI-associated rs9991328 SNP in FAM13A is different from all other SNPs linked to human chronic lung diseases." (PMID 30301961, 2019). "However, despite this overlap of FAM13A contribution to chronic lung diseases, the several FAM13A variants have various impacts." (PMID 31900205, 2020). "Variants in FAM13A, as well as PARK2 and RGS6, have been associated with chronic lung disease in prior genome-wide association studies (GWAS)." (PMID 28178938, 2017). "The aim of this study was to identify the protein partners of the isoform 1 of FAM13A protein in order to decipher the pathways that may be affected in the different chronic lung diseases." (PMID 31900205, 2020). "The role of FAM13A in chronic lung diseases starts to be elucidated in various studies." (PMID 31900205, 2020). "The future study of these interactions may help to not only understand the overlapping role of FAM13A in chronic lung diseases but their etiology as well." (PMID 31900205, 2020).
non-small cell lung carcinoma (3 papers, 2021). A group of at least three distinct histological types of lung cancer, including non-small cell squamous cell carcinoma, adenocarcinoma, and large cell carcinoma. "The aim of the present study is therefore to investigate the biological role of hypoxia-induced FAM13A in non-small cell lung cancer (NSCLC) progression." (PMID 33919074, 2021). "In non-small lung cell cancer, FAM13A was reported to be involved in tumor proliferation downstream of HIF (Hypoxia Inducible Factor)-1α and TGF-β." (PMID 33573279, 2021). "Studies on FAM13A in cell proliferation are rarely reported, and most studies are focused on COPD and non-small cell lung cancer (NSCLC)." (PMID 34672860, 2021).
lung adenocarcinoma (2 papers, 2020 to 2021). A carcinoma that arises from the lung and is characterized by the presence of malignant glandular epithelial cells. "Among patients with lung adenocarcinoma and squamous cell carcinoma, increased FAM13A levels were found in tumoral area of the lung." (PMID 33919074, 2021).
pulmonary hypertension (2 papers, 2020 to 2021). Increased pressure within the pulmonary circulation due to lung or heart disorder. "Consistent with the exacerbated pulmonary hypertension, vascular remodeling such as increased fully muscularized small diameter vessels and loss of peripheral capillaries was worsened in the lungs of Fam13a-/- mice as compared to those in WT mice." (PMID 32053709, 2020). "Genetic loss of FAM13A exacerbated pulmonary hypertension in mice exposed to chronic hypoxia in association with deteriorated pulmonary artery remodeling." (PMID 32053709, 2020). "Given that Fam13a was reduced in the lungs of mice with pulmonary hypertension, and genetic loss of FAM13A exacerbated pulmonary hypertension, enhancing and/or preserving FAM13A in the lungs might have a therapeutic potential." (PMID 32053709, 2020). "Nonetheless, our in vivo data using Fam13a-/- mice clearly showed that loss of FAM13A exacerbated pulmonary hypertension, and thus FAM13A is an attractive pharmacotherapeutic target for the treatment of pulmonary hypertension." (PMID 32053709, 2020). "To assess a possible involvement of FAM13A in the pathogenesis of pulmonary hypertension, we analyzed Fam13a expression in the lungs of mice with pulmonary hypertension." (PMID 32053709, 2020). "In this manuscript, we revealed a previously undescribed role of FAM13A in the development of pulmonary hypertension." (PMID 32053709, 2020). "In the current study, we have identified a protective role of FAM13A in the progression of pulmonary hypertension by utilizing mice in which Fam13a was genetically deleted." (PMID 32053709, 2020). "When exposed to chronic hypoxia, Fam13a-/- mice showed deteriorated pulmonary hypertension assessed by higher right ventricular systolic pressure and increased Fulton index." (PMID 32053709, 2020). "In addition, in the pulmonary hypertension model, FAM13A can alleviate EMT of endothelial cells by inhibiting the β-catenin signaling of pulmonary artery endothelial cells." (PMID 34210319, 2021). "FAM13A expression was reduced in the lungs of mice with hypoxia-induced pulmonary hypertension." (PMID 32053709, 2020). "Here, we identified a significant role of FAM13A in the development of pulmonary hypertension." (PMID 32053709, 2020). "Our data revealed a protective role of FAM13A in the development of pulmonary hypertension, and therefore increasing and/or preserving FAM13A expression in pulmonary artery endothelial cells is an attractive therapeutic strategy for the treatment of pulmonary hypertension." (PMID 32053709, 2020). "Because FAM13A is expressed in variety types of cells in the lungs, other FAM13A-mediated cellular processes might be involved in the pathogenesis of pulmonary hypertension." (PMID 32053709, 2020). "We then explored a role of FAM13A in pulmonary hypertension using Fam13a-/- mice." (PMID 32053709, 2020).
Airway obstruction (1 paper, 2021). Obstruction of conducting airways of the lung. "These are consistent with previous reports concluding that FAM13A may be a potential EMT-correlated airway obstruction susceptibility gene." (PMID 34210319, 2021).
breast carcinoma (1 paper, 2023). "In particular, the association of FAM13A rs1059122 with a reduced risk of breast cancer in a recessive model may contribute to susceptibility to breast cancer in the Chinese Han population." (PMID 37391706, 2023).
Cirrhosis (1 paper, 2019). A chronic disorder of the liver in which liver tissue becomes scarred and is partially replaced by regenerative nodules and fibrotic tissue resulting in loss of liver function. "The results demonstrate that FAM13A genetic polymorphisms are associated with cirrhosis risk, which indicate that the FAM13A gene may play an important role in the risk of liver cirrhosis in the Chinese population." (PMID 30604588, 2019).
colorectal cancer (1 paper, 2017). A primary or metastatic malignant neoplasm that affects the colon or rectum. "Three of these genes (Rgs16, Rassf3 and Fam13a) are members of the RAC/RHO/RAS pathway, and dysregulated Rgs16 has been associated with poor prognosis in colorectal cancer." (PMID 28219480, 2017).
COVID-19 (1 paper, 2025). A disease caused by infection with severe acute respiratory syndrome coronavirus 2. "These variants and FAM13A rs2609255 were also related to pulmonary function post-COVID-19." (PMID 40076669, 2025). "This study aims to identify the association of FAM13A, DSP, TOLLIP, TERT, and THSD4 variants with severe COVID-19 and post-COVID-19 condition in a Mexican mestizo population." (PMID 40076669, 2025). "The well-known variants in recognized genes related to pulmonary function worsening (THSD4 rs872471) and interstitial disorders (FAM13A rs2609255, DSP rs2076295, TERT rs2736100) are related to the severity and mortality of COVID-19 and lung performance in the post-COVID-19 condition." (PMID 40076669, 2025). "Moreover, FAM13A is involved in the TGF-β1-induced fibrotic response in the airway epithelium, which is recognized as the dominant chronic immune response in COVID-19." (PMID 40076669, 2025). "These biological routes, including those involving the FAM13A, DSP, TOLLIP, TERT, and THSD4 genes, have not been entirely studied in COVID-19 and post-COVID-19 condition." (PMID 40076669, 2025).
diabetes (1 paper, 2022). "Our list is supported by colocalization of genes known to lead to Mendelian forms of diabetes (e.g., SLC2A2 and WFS1) and of genes with previously demonstrated mechanisms of association with IR/T2D (e.g., METAP2, PLEKHA1 [TAPP1], FAM13A, and KLF14)." (PMID 35292083, 2022).
hyperlipidemia (1 paper, 2019). "Interestingly, another study using WGCNA identified FAM13A as a hub gene related to hyperlipidemia." (PMID 31086608, 2019).
liver cirrhosis (1 paper, 2019). "The polymorphisms of rs3017895 and the rs1059122 in FAM13A are associated with an increased risk of liver cirrhosis." (PMID 30604588, 2019). "In our study, we investigated two SNPs in FAM13A, including rs3017895 and rs1059122, and we find the SNPs in FAM13A gene were associated with an increased the risk liver cirrhosis." (PMID 30604588, 2019). "Therefore, we performed a case–control study to analyze the association between the FAM13A and the risk of liver cirrhosis." (PMID 30604588, 2019). "The aim of this study was to explore whether FAM13A polymorphisms confer susceptibility to liver cirrhosis." (PMID 30604588, 2019). "Our findings demonstrated that the high expression of FAM13A may be associated with an increased risk of liver cirrhosis." (PMID 30604588, 2019). "However, no studies have investigated the association between genetic variants in FAM13A and the risk of liver cirrhosis." (PMID 30604588, 2019). "The results showed that the expression of FAM13A is obvious higher in the liver cirrhosis tissue cells than in the normal liver tissue cells." (PMID 30604588, 2019). "Our results indicate that the expression level of FAM13A in liver cirrhosis tissues was significantly higher than the normal tissues." (PMID 30604588, 2019). "We found that the expression level of FAM13A in liver cirrhosis tissues was significantly higher than the normal tissues." (PMID 30604588, 2019). "A limited number of studies has been conducted on the FAM13A gene expression to identify a potential novel biomarker for liver cirrhosis." (PMID 30604588, 2019). "FAM13A expression was evaluated in liver cirrhosis tissues by immunohistochemistry staining." (PMID 30604588, 2019). "However, studies about the FAM13A and other diseases have not been reported, including liver cirrhosis." (PMID 30604588, 2019).
lymph node metastasis (1 paper, 2023). "We did not observe significant differences in the FAM13A gene between various clinical characteristics, including clinical stage (p = 0.1371), tumour (p = 0.6249), and lymph node metastasis (p = 0.1923)." (PMID 37391706, 2023).
mastitis (1 paper, 2014). Inflammation of breast tissue during lactation or postpartum due to an obstructed duct or infection. "This region also includes the FAM13A (family with sequence similarity 13, member A) gene, which has been shown to be associated with mastitis in Jersey cows." (PMID 24788864, 2014).
oral cancer (1 paper, 2023). "In this project, we will examine the presence of gene polymorphisms gene polymorphisms of rs1059122, rs3017895, rs3756050, and rs7657817 in the FAM13A gene exon, and combine the expression of these genes to try to clarify the impact of the FAM13A gene polymorphism on oral cancer." (PMID 37391706, 2023). "The results of this study indicate a significant difference in the SNP located in the FAM13A gene between oral cancer patients and the control group." (PMID 37391706, 2023).
Simpson-Golabi-Behmel syndrome (1 paper, 2020). Simpson-Golabi-Behmel syndrome is a rare X-linked multiple congenital anomalies syndrome, characterized by pre- and postnatal overgrowth, distinctive craniofacial features, variable congenital malformations, organomegaly and an increased tumor risk. "To translate the potential role of FAM13A into a human cell model of adipocytes, we studied the expression and function of FAM13A during the differentiation of Simpson-Golabi-Behmel syndrome (SGBS) preadipocytes – a cell line isolated from subcutaneous depots of an infant with SGBS17." (PMID 32193374, 2020).
tumor (10 papers, 2011 to 2023). "Inhibition of FAM13A in NSCLC inhibits tumour cell proliferation, FAM13A levels are directly associated with HIF-1α levels, and FAM13A is located downstream of HIF-1α." (PMID 34672860, 2021). "It was hypothesized that FAM13A together with HIF1α might be associated with antitumor effector T cells in the control area surrounding the growing tumor, in which oxygen deprivation occurred." (PMID 33919074, 2021). "Although little is known about FAM13A function, the Rho GTPase activating role suggests both anti-inflammatory and tumor suppressor activity." (PMID 37107672, 2023). "If FAM13A overexpression plays an adaptative role to hypoxia in cancer cells, silencing of this gene should have more severe effect on features of primary tumor cells." (PMID 33919074, 2021). "Studies have reported that fam13a is related to the occurrence of NSCLC, and siRNA to FAM13A infected tumour cell promotion." (PMID 34672860, 2021). "Further studies are necessary to better understand the role of FAM13A in programmed tumor cell death." (PMID 33919074, 2021). "Set of 19 genes, including FAM13A, was induced by hypoxia in primary tumor and remained overexpressed at metastatic site in the lung, suggesting occurrence of a ‘hypoxic memory’." (PMID 33919074, 2021). "Accordingly, FAM13A has been involved in multiple biological processes such as epithelial cell regeneration, tumor cell proliferation and survival, and insulin signaling." (PMID 32053709, 2020). "Although little is known of the FAM13A function, the Rho GTPase activating role suggests both anti-inflammatory and tumor suppressor activity for FAM13A protein." (PMID 26310313, 2015). "The FAM13A protein, expressed in respiratory cells, is thought to be involved in signal transduction with possible tumor suppressor activity." (PMID 21304900, 2011). "To summarize, very little is known about the role of FAM13A gene on tumor cellular proliferation." (PMID 33919074, 2021). "FAM13A is involved in tumour cell promotion and downstream of TGFβand HIF1." (PMID 34672860, 2021). "It is suggested that the most important part of the FAM13A protein is its N-terminal extension containing the Rho-GAP domain, which presents tumour suppressor activity through inhibition of the intracellular signal transduction molecule RhoA18." (PMID 26310313, 2015). "While these findings clearly indicate an important role of FAM13A in regulating tumor or (pre)adipose cell numbers, they seem to be opposite to our finding which suggests a negative role of FAM13A in regulating the survival of adipose precursors." (PMID 30301961, 2019).
cancer (4 papers, 2017 to 2021). A tumor composed of atypical neoplastic, often pleomorphic cells that invade other tissues. "The effect of FAM13A inhibition on cell migration/invasion can be related to great plasticity of cancer cells in their movement mechanisms and to the activation of other signaling pathways involved in cell migration, e.g., Rac GTPase-mediated signaling." (PMID 33919074, 2021). "To analyze the role of FAM13A in cancer cell metastasis, we performed wound healing and invasion assays." (PMID 33919074, 2021). "Thus, we demonstrated that FAM13A silencing modulates the growth of cancer cells in hypoxia conditions." (PMID 33919074, 2021). "Similar associations with ERG have also been found for other FAM members, including FAM77C and FAM13A that are up regulated in the presence of ERG, or for FAM111B, FAM3B and FAM124B that are down-regulated in ERG positive cancers." (PMID 28415558, 2017). "Indeed, the proteins identified to interact with FAM13A may be specific of the cancer origins of the cells and my different in a non-pathological context." (PMID 31900205, 2020).
metabolic disease (2 papers, 2023 to 2025). A congenital disorder (due to inherited enzyme abnormality) or acquired (due to failure of a metabolically important organ) disorder resulting from an abnormal metabolic process. "Until now, polymorphisms such as Pro12Ala, C1431T (both in PPAR-γ2), and Trp64Arg (β3-AR) were mainly associated with metabolic disorders, while FAM13A gene variants (rs1903003, rs7671167, rs2869967) were more prevalent in COPD." (PMID 37107672, 2023). "Gene annotation based on the TWAS database highlighted significant associations between several of these candidate genes (such as SPP1, FAM13A, NDRG1, and IER3) and key bovine health traits, including milk protein percentage, body depth, and ketosis (a metabolic disease of dairy cow) susceptibility." (PMID 40521032, 2025).
respiratory diseases (1 paper, 2024). "We also show that the long FAM13A isoform coordinates cilia-driven movement, suggesting that FAM13A risk alleles may affect susceptibility to respiratory diseases through deficiencies in mucociliary clearance." (PMID 38691660, 2024).